TNKS (tankyrase)
Description:
Poly-ADP-ribosyltransferase involved in various processes such as Wnt signaling pathway, telomere length and vesicle trafficking. Acts as an activator of the Wnt signaling pathway by mediating poly-ADP-ribosylation (PARsylation) of AXIN1 and AXIN2, 2 key components of the beta-catenin destruction complex: poly-ADP-ribosylated target proteins are recognized by RNF146, which mediates their ubiquitination and subsequent degradation. Also mediates PARsylation of BLZF1 and CASC3, followed by recruitment of RNF146 and subsequent ubiquitination. Mediates PARsylation of TERF1, thereby contributing to the regulation of telomere length. Involved in centrosome maturation during prometaphase by mediating PARsylation of HEPACAM2/MIKI. May also regulate vesicle trafficking and modulate the subcellular distribution of SLC2A4/GLUT4-vesicles. May be involved in spindle pole assembly through PARsylation of NUMA1. Stimulates 26S proteasome activity.
Synonyms: ARTD5; PARP5A; PARPL; TIN1; TINF1; TNKS1; PARP-5a; pART5
Tractability: Small molecule: a drug acting on it is in phase 2 or 3 trials; a structure with a bound ligand is known; a high-quality ligand is known; it belongs to a druggable protein family. Antibody: UniProt places it where antibodies can reach, with high confidence. PROTAC: UniProt records ubiquitination sites on it; ubiquitination databases record sites on it; its protein half-life has been measured; a small molecule that binds it is known.
Target class: Enzyme; Transferase
Chemical probes: AZ6102 (high quality), E7449 (high quality), JW55, PD134683, XAV939
Gene: Protein-coding gene on chromosome 8 (9,555,912 to 9,782,346, forward strand). Ensembl gene ENSG00000173273.
Subcellular location: Cytoplasm; Golgi apparatus membrane; Cytoplasm, cytoskeleton, microtubule organizing center, centrosome; Nucleus, nuclear pore complex; Chromosome, telomere; Cytoplasm, cytoskeleton, spindle pole
Subcellular location (Human Protein Atlas): Nucleoplasm; Nuclear bodies; Nuclear membrane
Pathways (Reactome):
Signal Transduction: Degradation of AXIN; Regulation of PTEN stability and activity; TCF dependent signaling in response to WNT
Disease: XAV939 stabilizes AXIN
Metabolism of proteins: Ub-specific processing proteases
Gene Ontology:
Molecular function: histone binding; NAD+ poly-ADP-ribosyltransferase activity; NAD+-protein mono-ADP-ribosyltransferase activity; protein binding; telomerase inhibitor activity; zinc ion binding; NAD+-protein-aspartate ADP-ribosyltransferase activity; NAD+-protein-glutamate ADP-ribosyltransferase activity
Biological process: negative regulation of maintenance of mitotic sister chromatid cohesion, telomeric; negative regulation of telomere maintenance via telomere lengthening; peptidyl-serine phosphorylation; peptidyl-threonine phosphorylation; positive regulation of canonical Wnt signaling pathway; positive regulation of telomere capping; positive regulation of telomere maintenance via telomerase; positive regulation of telomere maintenance via telomere lengthening; positive regulation of transcription by RNA polymerase II; protein auto-ADP-ribosylation; protein localization to chromosome, telomeric region; protein poly-ADP-ribosylation; protein polyubiquitination; regulation of telomere maintenance via telomerase; mitotic spindle organization; spindle assembly
Cellular component: chromosome, telomeric region; cytoplasm; Golgi apparatus; Golgi membrane; mitotic spindle pole; cytosol; nuclear membrane; nuclear pore; nucleus; pericentriolar material; centrosome; nuclear envelope; spindle pole
Genetic constraint (gnomAD): Loss-of-function variants: 53 observed, 104.29 expected, observed/expected ratio (o/e) 0.51, 90% interval 0.41 to 0.64. The synonymous counts are far from expectation, so gnomAD's model fits this gene poorly and the ratio says little. Missense variants: 1,598 observed, 1,568.1 expected, observed/expected ratio (o/e) 1.02, 90% interval 0.98 to 1.06. Synonymous variants: 782 observed, 623.01 expected, observed/expected ratio (o/e) 1.26, 90% interval 1.18 to 1.33.
Homologues: Orthologues: chimpanzee TNKS (99% identical), macaque TNKS (99% identical), dog TNKS (99% identical), rabbit TNKS (99% identical), guinea pig TNKS (98% identical), mouse Tnks (97% identical), rat Tnks (95% identical), pig TNKS (94% identical), tropical clawed frog tnks2 (88% identical), zebrafish tnksa (83% identical), zebrafish tnksb (82% identical), Drosophila melanogaster Tnks (59% identical), and 1 more. Paralogues in human: TNKS2 (71% identical), ANKRD45 (6% identical).
Diseases named in the same sentence as TNKS in open-access papers:
TNKS is named in the same sentence as 106 diseases in open-access papers, as found by Europe PMC text mining. Sharing a sentence is not in itself a finding about the gene and the disease. The quoted sentences say what the papers report.
colorectal cancer (43 papers, 2011 to 2025). A primary or metastatic malignant neoplasm that affects the colon or rectum. "Tankyrase inhibitors are a class of small molecule inhibitors that lower the elevated beta-catenin levels implicated in the proliferative pathobiology of colorectal cancer and appear to induce condensates." (PMID 36483537, 2022). "Concordantly, loss of AXIN2 disrupted regulation of AXIN1 expression by TNKS in SW480 colorectal cancer cells, which may have therapeutic implications for colorectal cancer through TNKS inhibitors." (PMID 39022865, 2025). "To explore the underlying mechanism mediating this effect we initially investigated cell growth in COLO320DM (APC mutated/KRAS WT) and HCT-15 (APC mutated/KRAS mutated) colorectal cancer cells under the influence of 1 μM G007-LK (TNKS inhibitor; TNKSi) and/or 1 μM GDC-0973 (MEK inhibitor; MEKi)." (PMID 30717152, 2019). "Comparison of the sensitivities of the four groups of colorectal cancer cell lines to representative porcupine inhibitors, tankyrase inhibitors, and EGFR inhibitors was performed using data from the GDSC project." (PMID 40061138, 2025). "Our experiments revealed that inhibition of Wnt signaling by TNKS small‐molecule inhibitors in SW480 colorectal cancer cells strictly depends on AXIN2." (PMID 39022865, 2025). "Utilizing Wnt/β-catenin signaling, hsa_circ_0005615 (circNFATC3) reinforces colorectal cancer cell behavior through increasing the expression of tankyrase (TNKS) by sponging miR-149-5p." (PMID 38892280, 2024). "The use of tankyrase inhibitors, which downregulate β-catenin activated by mutations in the APC gene, was reported to be an efficient treatment for colorectal cancer patients." (PMID 36831263, 2023). "The tankyrase inhibitor XAV939 reversed 5-fluorouracil chemoresistance by targeting the WNT/β-catenin signaling pathway in colorectal cancer cells." (PMID 36827121, 2023). "The antiproliferation assay demonstrated that NSC319963 can decrease colorectal cancer cell growth; therefore, the proposed method successfully identified a novel TNKS inhibitor that can alleviate CRC." (PMID 35052822, 2022). "The restoration of β-catenin degradation in APC-mutated cells after the treatment with G007-LK was shown, providing a link between TNKS inhibition and degradasomes formation in colorectal cancer cells." (PMID 33910596, 2021). "For both genes, endometrial is the one that presented the highest rate of TNKS and TNKS2 mutations, followed by colorectal cancer, bladder and esophagogastric (for TNKS) and melanoma, colorectal and prostate (for TNKS2)." (PMID 33910596, 2021). "To date, many selective TNKS inhibitors with different structures and binding modes have been developed and used to treat colorectal cancer." (PMID 33910596, 2021). "Here, we generated tumour organoids from colorectal cancer patients and tested their responses to inhibitors of Tankyrase (TNKSi) which are known to modulate Wnt signalling." (PMID 32810173, 2020). "Our data in colorectal cancer cell lines, suggests that downstream induction of the WNT pathway by activating mutations in CTNNB1 are sufficient to overcome the effects of TNKS blockade." (PMID 31891587, 2019). "Development of TNKS inhibitors has therefore gained increasing attention as a treatment strategy for WNT induced colorectal cancer." (PMID 30717152, 2019). "Given the interest in using tankyrase inhibitors to target APC mutant colorectal cancers (CRC), we also assessed MSC2504877 sensitivity in a panel of CRC tumour cell lines." (PMID 30655555, 2019). "We identify CDK4 as a synthetic vulnerability in colorectal cancer cells and show that dual inhibition of TNKS and CDK4 drives a potent cell cycle arrest in a range of human epithelial cancer cell lines including colon, breast and lung cancer cells." (PMID 31891587, 2019).
colorectal cancer (continued). "Since tankyrase positively regulates Wnt/β-catenin signaling, tankyrase inhibitors have been expected to be novel anticancer therapeutics, especially for Wnt-driven colorectal cancer." (PMID 30533199, 2018). "Here we review some of the latest advances in our understanding of tankyrase function in the pathway and efforts to modulate tankyrase activity to re‐tune Wnt/β‐catenin signalling in colorectal cancer cells." (PMID 28910490, 2017). "Collectively, this study reveals a redox mechanism for regulating tankyrase activity and implicates PrxII as a targetable antioxidant enzyme in APC-mutation-positive colorectal cancer." (PMID 28659575, 2017). "Accordingly, tankyrase inhibitors are under preclinical development for colorectal cancer (CRC) therapy." (PMID 28615517, 2017). "Here the authors show that in colorectal cancers with APC mutation, PrxII binds to tankyrase and prevents its oxidative inactivation, thereby preventing Axin1-dependent degradation of 2b-catenin." (PMID 28659575, 2017). "Here we demonstrate that Prx type II (PrxII) plays a tumor-promoting role in colorectal cancer by interacting with a poly(ADP-ribose) polymerase (PARP) tankyrase." (PMID 28659575, 2017). "Previous studies have shown that tankyrase inhibitors abrogate Wnt signalling in colorectal cancer cells with mutant APC." (PMID 23144924, 2012). "Consistent with reported results on APC-mutant colorectal cancer cells, tankyrase inhibitors stabilized Axin1 expression in DU4475 breast cancer cells, that harbor a mutant APC." (PMID 23144924, 2012). "In colorectal cancer cells, which typically harbor APC mutations, inhibition of tankyrase activity promotes Axin stabilization and attenuates Wnt signalling." (PMID 23144924, 2012). "Colorectal cancer cell line HCT-15 is activated for Wnt signaling by an APC truncating mutation, and signaling is partially inhibited by tankyrase RNAi." (PMID 21799911, 2011). "Lastly, in the colorectal cancer cell line SW480 that also possesses a truncating APC mutation, tankyrase RNAi stabilizes AXIN1, AXIN2, and RNF146 proteins." (PMID 21799911, 2011). "These considerations might become relevant for future colorectal cancer therapy by TNKS small‐molecule inhibitors." (PMID 39022865, 2025). "In addition, mice xenografts and patient-derived sphere cultures of colorectal cancer (CRC) were treated with the tankyrase inhibitor NVP-TNKS656 in conjunction with AKT and PI3K inhibitors to downregulate β-catenin levels and induce apoptosis." (PMID 40699862, 2025). "Taken together, our data suggest that AXIN2 promotes degradation of AXIN1 through TNKS in colorectal cancer cells by directly linking the two proteins, and these findings may be relevant for TNKS inhibition‐based colorectal cancer therapies." (PMID 39022865, 2025). "In contrast to cancers with APC or other defects in the β-catenin destruction complex, colorectal cancers with RNF43 mutations may retain WNT pathway ligands dependence and may as a result be better targets for porcupine and tankyrase inhibitors." (PMID 40061138, 2025). "Here the work shows TFRC is induced by adenomatous polyposis coli (APC) gene loss‐driven β‐catenin activation in colorectal cancer, whereas TFRC‐mediated intratumoral iron accumulation potentiates β‐catenin signaling by directly enhancing the activity of tankyrase." (PMID 36703617, 2023). "Therefore, Tankyrase inhibitors function as inducer c-mods of the beta-catenin destruction complex condensates that regulate Wnt signal transduction in colorectal cancer." (PMID 36483537, 2022). "Other option could be the use of TNKS inhibitors as a combination therapy to enhance their antitumor effect in colorectal cancer models that are resistant to TNKS inhibition." (PMID 33910596, 2021). "The application of tankyrase inhibitors may be particularly useful for treating Wnt-dependent cancers, especially colorectal cancer." (PMID 30813388, 2019).
colorectal cancer (continued). "When a tankyrase inhibitor (G-631) was administered in a murine xenograft colorectal cancer model, the inhibitor exhibited an anti-cancer effect, but it simultaneously induced severe intestinal toxicity, characterized by multifocal-regionally extensive necrotizing and ulcerative enteritis." (PMID 30813388, 2019). "Although inhibition of TNKS activity has been shown to block Apc mutant colorectal cancer development, we found that the organoids derived from the polys of Villin-Cre;Apc+/fl mice showed normal cell proliferation and activation of Wnt/β-catenin signaling in the presence of XAV939." (PMID 30260955, 2018). "Puncta also were observed for endogenous Tankyrase in XAV939-treated colorectal cancer cells." (PMID 27494558, 2016). "This hints that TNKS/2-directed drugs are likely to prove effective as inhibitors of Wnt signals only in those tumors that display constitutive Wnt activation on a genetic basis, such as colorectal cancer." (PMID 26787475, 2016). "Because our data pointed to an essential role for AXIN2 in regulating the Wnt pathway in colorectal cancer cells, we investigated the particular relevance of AXIN2 for Wnt pathway inhibition by TNKS small‐molecule inhibitors in these cells." (PMID 39022865, 2025). "Docking scores of all synthesised compounds (15a–r) in the catalytic binding pocket of tankyrase and PI3K receptor in colorectal cancer (PDB IDs: 4OA7 and 3L54)." (PMID 36364474, 2022). "Anticancer treatment, using small-molecule tankyrase 1 and tankyrase 2 (TNKS1/2) inhibitors, shows in vivo efficacy against colorectal cancer and osteosarcoma in mouse xenograft models." (PMID 34337362, 2021). "The reduction of Wnt/β-catenin signaling, by the tankyrase inhibitors G007-LK and G244-LM, has been also demonstrated in APC mutant colorectal cancer (CRC) cell lines." (PMID 26056602, 2015). "In control RKO colorectal cancer cells a similar, though more potent inhibition of the TOPFLASH reporter was observed upon abrogation of tankyrase 1 or tankyrase 2 expression." (PMID 23144924, 2012). "TNKS small‐molecule inhibitors block Wnt/β‐catenin signaling by stabilizing AXIN1 and AXIN2, and have therefore been investigated for targeted treatment of colorectal cancer." (PMID 39022865, 2025). "Combining tankyrase inhibitors with other targeted therapies, such as PI3K inhibitors (e.g., BKM120) and EGFR inhibitors (e.g., erlotinib), has been proposed as a promising approach for treating APC-mutant colorectal cancers." (PMID 40001540, 2025). "In the present study, we noted that TNKS inhibition through the broadly used TNKS inhibitor G007‐LK failed to inhibit Wnt/β‐catenin signaling in AXIN2 knockout colorectal cancer cells." (PMID 39022865, 2025). "Tankyrase inhibitors (e.g., XAV939, IWR-1, G007-LK) have shown potential by stabilizing substrates like Axin1/2 and suppressing hyperactive Wnt/β-catenin signaling, frequently observed in colorectal cancer and hepatocellular carcinoma." (PMID 40001540, 2025). "Therefore, based on the immunofluorescence assay, Western blot assay, and docking results, it appears that conjugates 15r and 15o act as dual inhibitors of tankyrase and PI3K in colorectal cancer." (PMID 36364474, 2022). "For example, miR-149-5p played a role in the has-circ-0005615/miR149-5p/TNKS axis in colorectal cancer and acted on the long noncoding RNA PART1/miR-149-5p/MAP 2K1 axis in hepatocellular carcinoma." (PMID 33224315, 2020). "Combining TNKS and RAS/MEK/ERK inhibition is therefore attractive strategies against colorectal cancer although induction of further feedback rescue mechanisms may require extensive combination of inhibitor treatments in order to fully eradicate the cancer." (PMID 30717152, 2019). "In SW480 colorectal cancer cells treated with the tankyrase inhibitor (TNKSi) G007-LK we found that AXIN1 was not required for degradasome formation." (PMID 28107521, 2017).
colorectal cancer (continued). "Furthermore, another biosynthetic enzyme inhibitor, XAV939 against tankyrase (TNKS), a regulator enzyme for Axin homeostasis, had been studied in colorectal cancer." (PMID 27570510, 2016). "The therapeutic effect can be enhanced and broadened by combining tankyrase inhibition (TNKSi) with inhibitors of phosphatidylinositol-4,5-bisphosphate 3-kinase (PI3K), epidermal growth factor receptor, or mitogen-activated protein kinase against colorectal cancer xenografts." (PMID 34337362, 2021). "However, Wnt-driven colorectal cancer cells are not equally sensitive to tankyrase inhibitors, and cellular factors that affect tankyrase inhibitor sensitivity remain elusive." (PMID 28615517, 2017). "Inhibition of the tankyrase enzymes (TNKS1 and TNKS2) has recently been shown to induce highly dynamic assemblies of β-catenin destruction complex components known as degradasomes, which promote degradation of β-catenin and reduced Wnt signaling activity in colorectal cancer cells." (PMID 28107521, 2017). "Indeed, there is cumulative evidence that pharmacologic neutralization of TNKS/2 activity proficiently (albeit not uniformly) impairs the growth of APC-mutant colorectal cancer cells by attenuating Wnt-mediated signals." (PMID 26787475, 2016). "Targeting TNKS by small molecule inhibitors including XAV939 and WIKI4 inhibits Wnt signaling and suppresses the malignant phenotypes including anchorage-independent growth in colorectal cancer cells, suggesting that TNKS is a potential target for treatment of Wnt-dependent cancers." (PMID 24594309, 2014). "In contrast, the recently described iron chelator, 21H7, which inhibits constitutive Wnt signalling and growth in colorectal cancer cells independent of tankyrase or Axin stabilization, blocked MDA-MB-231, DLD-1 and SW480 cell growth with IC50s in the range of 0.6–1.0 μM, as expected." (PMID 23144924, 2012). "Moreover, the high AXIN2 dependency of Wnt pathway inhibition by TNKS inhibitors in colorectal cancer cells implies that TNKS inhibitors will never block Wnt signaling completely because this would prevent transcription of the β‐catenin target gene AXIN2, causing AXIN2 depletion." (PMID 39022865, 2025). "Chemically induced degradation of TNKS overcomes this limitation by stabilizing AXIN without puncta formation, providing a deeper suppression of the WNT/β-catenin pathway activity and the proliferation of colorectal cancer cells harboring dysfunctional APC mutations." (PMID 41040241, 2025). "The synergy between TNKS and CDK4 inhibition was not restricted to DLD1 cells, as we observed similar effects of TNKS silencing and Trametinib or Palbociclib treatment in the colorectal carcinoma cell line SW480 (bearing an APC truncating mutation, similar to DLD1)." (PMID 31891587, 2019). "Remarkably, however, expression of axin proteins above a certain threshold, e.g., by overexpression or stabilization by tankyrase inhibition suffices to degrade β-catenin in the absence of APC and blocks colorectal cancer proliferation." (PMID 31534175, 2019).